C5 (complement C5)
Diseases named in the same sentence as C5 in open-access papers (continued):
Sharing a sentence is not in itself a finding about the gene and the disease.
C3 glomerulopathy (15 papers, 2012 to 2025). "In Cfh−/− mice (a model of C3 glomerulopathy, a kidney disease caused by the AP dysregulation), the ablation of C5 improves survival and reduces glomerular inflammation (mediated by C5a), but does not reduce proteinuria or glomerular C3 staining." (PMID 27199983, 2016). "Cfh−/− mice injected with anti-C5 antibodies before administration of nephrotoxic serum also were protected, suggesting that anti-C5 therapy may be beneficial in human beings with C3 glomerulopathy owing to Cfh deficiency (eg, during disease flares)." (PMID 24161036, 2013). "The role of C5 is also being studied in C3 glomerulopathy, a rare disease of the kidney in which acquired autoantibodies target the C3 or C5 convertases, dysregulating complement activation." (PMID 41189475, 2025). "In the current study, LoCHO_FAT food decreased complement C5, and blockade of C5 has been reported to attenuate renal failure, including C3 glomerulopathy, an abnormal complement activation, in mice." (PMID 38590952, 2024). "FD inhibitors should also be evaluated in clinical trials either as add-on therapy for C3 glomerulopathy patients, or for aHUS patients in whom C5 inhibition is insufficient, or as an alternative therapy." (PMID 34177949, 2021). "An essential role of C5 has been demonstrated in animal models of membranoproliferative glomerulonephritis and C3 glomerulopathy, but rather through effects of C5a on its receptor than formation of C5b-9." (PMID 33643288, 2020). "Autoimmune factors in C3 glomerulopathy include autoantibodies in form of C3-Nephritic Factor, C4-Nephritic Factor or C5-Nephritic Factor." (PMID 31611870, 2019). "In many cases of C3 glomerulopathy, the deposition of C3 in glomeruli leads to subsequent activation of C5 and there is considerable interest in the possibility of using the anti-C5 antibody eculizumab for treatment." (PMID 28357053, 2017). "In addition, C4-convertase (C4-Nef), as well as C5-convertase (C5-Nef), targeting autoantibodies are described in C3 glomerulopathy." (PMID 34613485, 2021). "Investigator initiated trials with C5 targeting by Eculizumab were reported for C3 glomerulopathy." (PMID 31611870, 2019). "Evidence from C3G animal models suggests alternative pathway activity in the absence of C5 reduces glomerular inflammation, but C3 glomerulopathy persists." (PMID 31701048, 2019). "C5 blockade protected C3KI mice from disease, and through long-term studies of C5 genetic deletion, we have shown that while increased C3 turnover continues through dysregulation of the alternative pathway, this does not evolve into a C3 glomerulopathy." (PMID 30714990, 2019).
lupus nephritis (15 papers, 2011 to 2025). Glomerulonephritis in the context of systemic lupus erythematosus. "Eculizumab, a monoclonal antibody binding C5, inhibiting its cleavage, and thus preventing formation of C5b-9, is used to treat aHUS and some cases of lupus nephritis, C3 glomerulonephritis, dense deposit disease, IgA nephropathy, and transplant rejection." (PMID 33643288, 2020). "If inadequate control of the complement system caused by genetic predisposition is involved in SLE nephritis, it could become an additional indication for use of the emerging complement inhibitors such as eculizumab, which is a monoclonal antibody inhibiting cleavage and activation of C5." (PMID 22171659, 2011). "Similarly, in lupus nephritis models, studies show increased survival and improved kidney disease with blockage of C5 and C5a receptors." (PMID 38895123, 2024). "Although we are aware that these observations require further validation with regard to protein expression and experimental models, here we link SGLT-2 and intrarenal synthesis of complement C5 in diabetic nephropathy, as it has also been recently described in experimental lupus nephritis." (PMID 38069385, 2023). "Eculizumab—a humanized recombinant monoclonal antibody—binds to C5, shows efficacy in managing refractory cases of CAPS, post-kidney transplant TMA, and lupus nephritis with TMA." (PMID 40429322, 2025). "Moreover, this is of particular interest since ongoing trials are currently testing efficacy and safety of anti-C5 antibodies (clinical trial: NCT04564339) and C5a receptor (C5aR) antagonists (clinical trial: NCT02151409) in patients with lupus nephritis." (PMID 37445814, 2023). "Notably, glomerular C5b9 has been shown to persist in lupus nephritis following complement activity cessation, so may not be a reliable marker of ongoing glomerular C5 activation in C3G as well." (PMID 31701048, 2019).
rheumatoid arthritis (15 papers, 2008 to 2023). A chronic, systemic autoimmune disorder characterized by inflammation in the synovial membranes and articular surfaces. "Immune-related genes complement component 5 (C5)/TRAF1 located on Chromosome 9q33–34 is identified as a risk factor for rheumatoid arthritis, uveitis in juvenile idiopathic arthritis, multiple autoimmune diseases such as SLE." (PMID 32093731, 2020). "In the present study, C5-rs17611 was found to be associated with PDR patients; meanwhile, rs17611 was also found to be associated with periodontitis and the GG genotype was linked with increased C5 levels in patients with rheumatoid arthritis." (PMID 26989329, 2016). "Interestingly, C5 deficiencies have been found to be associated with rheumatoid arthritis, which is a common age-associated disease." (PMID 37341993, 2023). "Furthermore, some of the C5 polymorphic variants were associated with an increased susceptibility to rheumatoid arthritis (RA), SLE, age macular degeneration and other diseases." (PMID 38002958, 2023). "For example, the humanized monoclonal antibody against C5 (eculizumab), which inhibits its cleavage to C5a and C5b, promoted a significant improvement in the clinical score of rheumatoid arthritis when administered intravenously." (PMID 36362117, 2022). "For example, GWAS have identified an association between rheumatoid arthritis and rs3761847, a SNP in an LD block that encompasses two genes that have been implicated in chronic inflammation: TRAF1 and C5." (PMID 27015630, 2016). "Furthermore, C5 gene has been found to affect susceptibility to several inflammatory conditions, including AMD, rheumatoid arthritis, and renal allograft outcomes." (PMID 26989329, 2016). "TNF receptor-associated factor-1 (TRAF1) and Complement 5 (C5) (TRAF1-C5) lie adjacent to one another on 9q33-34 chromosome and confer susceptibility to diseases such as rheumatoid arthritis (RA) and systemic lupus erythematosus (SLE)." (PMID 23710202, 2013).
Stroke (14 papers, 2010 to 2024). Sudden impairment of blood flow to a part of the brain due to occlusion or rupture of an artery to the brain. "Activation of complement components such as C3 and C5 has also been linked to platelet-mediated thrombosis with implications for disease development including, but not limited to, myocardial infarction, stroke, PE, and venous thromboembolism." (PMID 37759718, 2023). "The C5 complement protein is a potent inflammatory mediator that has been implicated in the pathogenesis of both stroke and neurodegenerative disease." (PMID 24386419, 2013). "Stroke studies demonstrate markers of inflammation (complement C5, C5a receptor) and oxidative stress (gp91Phox, 8 hydroxyguanasine) in the region of the ischemic penumbra after 45 cumulative hours of nPM exposure." (PMID 34868068, 2021). "In patients suffering a stroke, plasma levels of C3a, C3, C4, C5, C5a, factor B, MBL, MASP-1/2, and MAC are all elevated and ficolin-1, ficolin-2, and ficolin-3 reduced." (PMID 31417544, 2019). "Compared to healthy volunteers, stroke patients were found to have higher plasma levels of C3a, C3, C4, C5, factor B, and the terminal complement complex." (PMID 26322048, 2015). "Experimental models of stroke result in elevated levels of complement components (C1q, C3a, C5a) in the brain and upregulation of C1q mRNA in microglia and C5 mRNA in neurons." (PMID 33239010, 2020). "The lifelong deficiency of C5 via genetic knock-out could result in a constitutionally detrimental effect since completely acute C5 blockade might mask a potential benefit in the context of stroke." (PMID 31011487, 2019). "Post‐stroke BHB therapy resulted in a substantial decrease in the expression of proinflammatory chemokines (CCL3, CXCL1, CXCL9, CXCL10), complement (C5/5a), cytokines (IFN‐γ), and myeloid cell activators (G‐CSF) in the ischemic hemisphere." (PMID 38666466, 2024). "Although stroke results in substantial BBB damage, RT-PCR evidence from primary neuronal cultures suggests that complement components such as C5 and then C5a can be produced by neurons and are upregulated after ischemic injury." (PMID 33239010, 2020). "In contrast, stroke induced a significant increase in maximal circulating concentrations of C1q, C5 and C9 in both IL-1Ra and placebo treated patients measured in the first seven days after stroke in comparison to non-stroke controls." (PMID 31700615, 2019). "Maximum circulating concentration of complement components associated with the classical and lectin pathways of activation, C1q, C2 and C4b, and end stage mediators common to all pathways, C5 and C9, were increased in the first seven days after stroke in comparison to non-stroke controls." (PMID 31700615, 2019).
thrombosis (14 papers, 2018 to 2026). "Monitoring the progression of any additional underlying illnesses is also crucial for patients receiving C5 inhibitors and experiencing thrombosis." (PMID 39596172, 2024). "Complement component 5 (C5) inhibitors have decreased PNH-related thrombosis rates and reduced mortality compared with those of age-matched controls." (PMID 38812989, 2024). "The thrombosis rate with C5 inhibitor ravulizumab treatment was 1.21 events per 100 patient-years among 434 patients in the extension period (662 patient-years of exposure)." (PMID 38812989, 2024). "Using C3−/− and C5−/− mice models, Subramaniam and colleagues (2017) reported that complement proteins participate in venous thrombosis after ligation of the inferior vena cava." (PMID 37543610, 2023). "In venous thrombosis, C5 promotes thrombosis by activating tissue factor activation." (PMID 36292752, 2022). "Mice deficient for C3 or C5 have reduced experimental venous thrombosis, with the lack of C5 not being accompanied by any defects in platelet activation or normal hemostasis." (PMID 29776849, 2018). "Eculizumab and ravulizumab prevent intravascular hemolysis and thrombosis among PNH patients however, more than 50% of patients with PNH on C5 inhibitors have mild to moderate symptoms from PNH, and up to 20% still need occasional transfusions." (PMID 40777953, 2024). "C5 inhibitors should be initiated in patients with PNH and thrombosis, while they constitute a great prophylactic measure for TEs in those individuals." (PMID 39596172, 2024). "We analyzed clinical data from PNH patients with or without thrombosis, including MUC4 mutation status and serum complement C5b‐9 levels." (PMID 41492103, 2026). "Despite receiving treatment with a C5 inhibitor, patients required PNH-related inpatient admissions, PNH-related blood transfusions, and experienced PNH-related thrombosis, suggesting a potential unmet need for more effective treatments among patients with PNH." (PMID 40827257, 2025). "It was reported that thrombosis in PNH patients could be resistant to the anticoagulant treatment, The anti-C5 humanized monoclonal antibody, such as ravulizumab, could be applied to prevent recurrent thrombosis." (PMID 40161390, 2025).
viral infection (14 papers, 2011 to 2025). "Significant signals for specific viral infections signals were most commonly reported with C5 inhibitors but showed the strongest statistical association with C3 inhibitors." (PMID 40860872, 2025). "Intriguingly, stratified ROR analysis revealed that C3 inhibitors exhibited significantly higher odds of viral infection reports relative to other classes (C5 and Factor B)." (PMID 40860872, 2025). "There exist significant differences in the number of reported viral infection adverse events across cases with different inhibitor groups, with the C5 inhibitor group having markedly more adverse cases than the C3 inhibitor and Factor B inhibitor groups." (PMID 40860872, 2025). "Employing robust pharmacovigilance algorithms, we detected significant disproportionality signals for viral infections, including influenza, herpes zoster, and gastroenteritis viral, most notably with C5 inhibitors." (PMID 40860872, 2025). "With viral infection alone, in control samples, C3 (P < 0.0021), C5 (P < 0.0001), and C1Inh (P < 0.0008) were significantly increased." (PMID 37534622, 2023). "A prerequisite for the C5 ORF to have a biological function is its expression in the context of viral infection." (PMID 37676365, 2022). "The ALCScV C5 protein, a protein that performs multiple functions during viral infection, is localized in both the cytoplasm and nucleus." (PMID 36060769, 2022). "Complement C5 is a central player in innate immunity, a process that prevents many bacterial, fungal and viral infections." (PMID 27105526, 2016). "If TMA recurs, anti-C5 therapy is restarted, and other etiologies (such as CNI, other medications, viral infections, AMR etc.)are investigated and treated." (PMID 40303217, 2025). "With the aim of assessing the biological relevance of the C5 protein in virus infection, we constructed a PVX-based recombinant vector carrying the C5 gene (PVX-C5) for ectopic overexpression of this viral sequence." (PMID 37676365, 2022). "Of note and in contrast to C5 inhibitory strategies, C1INH treatment has not been associated with an increased risk for bacterial or viral infections or any effect on viral replication." (PMID 37965347, 2023). "YFP-C5 transgenic plants inoculated with TYLCV exhibited more severe leaf curling symptoms and accumulated higher levels of viral DNA and protein, indicating that the expression of C5 facilitates viral infection." (PMID 37676365, 2022). "Though the exact function of C4 and C5 genes is still not known, C4 protein participates in suppression of RNA silencing mechanisms and C5 protein, which is not common, may be involved in replication of DNA but remains insignificant in viral infection." (PMID 30954067, 2019). "Nevertheless, the identification of an effect as well as the fact that c5 appear to reduce the PVX latent period and delay the onset of recovery indicates that further studies are warranted to investigate the potential contribution this gene product has for the viral infection cycle." (PMID 21592402, 2011).
hemolysis (13 papers, 2014 to 2025). Disruption of the integrity of the erythrocyte membrane causing release of hemoglobin. "Blocking complement with the humanized anti-C5 monoclonal antibody eculizumab is very good at reducing intravascular hemolysis, lowering the risk of thrombosis, and lowering the need for transfusions, all of which improve quality of life." (PMID 39295707, 2024). "There are several reasons that the incidence of TST in PNH will decrease over time: (i) eculizumab, a humanized monoclonal antibody against C5, blocks complement-mediated intravascular hemolysis and considerably decreases the risk of thrombosis." (PMID 24673826, 2014). "Although a major component of CA‐mediated hemolytic anemia is extravascular, sometimes the C3b complement activates C5, proceeding to major attack complex formation and leading to intravascular hemolysis." (PMID 41036160, 2025). "Our case highlights a novel application of eculizumab in refractory wAIHA associated with complement mediated hemolysis in which terminal complement components, including C5, are involved in the pathogenesis of intravascular hemolysis." (PMID 27092282, 2016). "The blockade of terminal complement pathway by eculizumab, a monoclonal antibody (moAb) against complement component 5 (C5), abrogates intravascular hemolysis with the consequent normalization of lactate dehydrogenase (LDH) levels in almost all patients suffering from PNH." (PMID 28629435, 2017).
geographic atrophy (12 papers, 2016 to 2026). "The C3 inhibitor pegcetacoplan and C5 inhibitor avacincaptad pegol has been FDA-approved as they are shown to significantly halt the atrophy progression in patients with geographic atrophy secondary to AMD." (PMID 39487449, 2024). "Among them, Zimura is a novel mono‐PEGylated anti‐C5 RNA aptamer, developed as a complement C5 inhibitor for treating geographic atrophy secondary to age‐related macular degeneration." (PMID 38193121, 2024). "Accordingly, anti-C3 and anti-C5 treatment are currently evaluated in late-stage clinical trials for geographic atrophy (GA) secondary to AMD71,72." (PMID 36371417, 2022). "It is also interesting that both anti-C3 and anti-C5 were given a label of ‘geographic atrophy’ despite the anti-C3 trials including both foveal and non-foveal involving lesions whilst in the anti-C5 trials, only non-foveal involving lesions were included." (PMID 39639153, 2025). "After numerous negative clinical trials, an anti-C5 agent and anti-C3 agent have recently shown promising results in phase 3 clinical trials in terms of slowing the growth of geographic atrophy." (PMID 35329812, 2022). "After numerous negative clinical trials, an anti-C5 agent and anti-C3 agent have recently shown promising results in phase 3 clinical trials, in terms of slowing the growth of geographic atrophy, an advanced form of AMD." (PMID 35329812, 2022). "Eculizumab and LFG316, which are monoclonal antibodies that target C5 and prevent its activation, have shown no reduction in the progression of geographic atrophy compared to controls." (PMID 32815311, 2020). "Recently a complement C3 inhibitor and a C5 inhibitor have been FDA approved for the treatment of geographic atrophy but have not demonstrated improvement in visual function, have produced some serious adverse events and barely reduce the growth rate of the geographic atrophy." (PMID 38045700, 2023). "While eculizumab, a humanized IgG antibody against complement component 5 (C5), seems to be ineffective in the management of dry AMD patients, treatment with lampalizumab, an antibody that inhibits complement factor D, reduced the progression of geographic atrophy lesion." (PMID 30225264, 2018).
age-related macular degeneration (11 papers, 2011 to 2026). Age-related loss of vision in the central portion of the retina (macula), secondary to retinal degeneration. "Avacincaptad Pegol: Avacincaptad pegol binds to and inhibits the C5 protein, and is administered every month as a treatment for complement-mediated eye diseases, such as age-related macular degeneration and Stargardt macular dystrophy." (PMID 34944087, 2021). "The anti-PDGF (platelet-derived growth factor) and the anti-C5 (complement component 5) RNA aptamers are used to treat macular edema and age-related macular degeneration." (PMID 27413756, 2016). "Histologically, DLDs have been demonstrated to react with antibodies against C5, TIMP3, vitronectin, and amyloid P component, which are the markers of age-related macular degeneration (AMD)-associated drusen, thus outlining a similarity between DLD and the typical drusen seen in patients with AMD." (PMID 37371724, 2023). "Drugs targeting the complement system, such as monoclonal AB against C3 or C5, have been tested in several clinical trials (phase II and III) for various diseases, including age-related macular degeneration." (PMID 34943212, 2021). "Similarly, another aptamer ARC1905 by Opththotech was developed to bind the complement component 5 (C5) and was used for the treatment of age-related macular degeneration (AMD)." (PMID 32659966, 2020). "Additionally, complement-mediated therapies for STGD1, similar to those being explored for age-related macular degeneration (AMD) and geographic atrophy, are also under investigation, such as the complement C5 inhibitor (NCT03364153)." (PMID 39860622, 2025).